SNHG4 (small nucleolar RNA host gene 4)
Diseases named in the same sentence as SNHG4 in open-access papers (continued):
Sharing a sentence is not in itself a finding about the gene and the disease.
tumor (25 papers, 2020 to 2025). "High levels of SNHG4 decreased overall survival (OS) and were distinctly linked to lymph node metastasis (P = 0.029) and the tumour stage (P = 0.014) of PCa patients." (PMID 34717631, 2021). "According to univariate analysis, stage, T classification, residual tumor, and SNHG4 expression were associated with poor relapse-free survival." (PMID 31967298, 2020). "According to univariate analysis, stage, T classification, residual tumor, and SNHG4 expression were associated with poor overall survival." (PMID 31967298, 2020). "High SNHG4 expression was positively linked to tumour size (P = 0.020)." (PMID 34717631, 2021). "In addition, SNHG4 expression was noticeably associated with tumour-node-metastasis (TNM) stage (P < 0.001), lymph node metastasis (P = 0.003), and tumour invasion (P = 0.004)." (PMID 34717631, 2021). "To discover the role of SNHG4 in GC, we downloaded and analyzed the TCGA RNA-seq data, which indicated that SNHG4 was expressed at a higher level in GC tumor compared to adjacent normal tissues." (PMID 39735673, 2025). "Studies have shown that the lncRNA small nucleolar RNA host gene 4 (SNHG4) serves as a tumor promoter in various malignancies, while its function in GC has yet to be characterized." (PMID 39735673, 2025). "Previous results indicated that exosomes derived from the serum of TNBC patients significantly upregulate lncRNA SNHG4, which in turn enhances tumor cell proliferation and migration." (PMID 40657248, 2025). "In previous research, SNHG4 can act as a ceRNA to participate in tumor progression by sponging miRNAs." (PMID 39951205, 2025). "There is a multi-targeting capability of the long noncoding RNA SNHG4, which also influences a variety of pathways that promote tumor malignancy." (PMID 39512820, 2024). "The results demonstrated that SNHG4 KD notably inhibited xenograft tumor growth in volume and weight, whereas RRM2 restoration partially recovered the growth of xenograft tumors." (PMID 37596700, 2023). "The correlation analysis of SNHG4 expression and clinicopathologic features of HCC patients displayed that higher SNHG4 expression were remarkably associated with larger tumor size, microvascular invasion, and higher TNM and Edmonson stages." (PMID 36565037, 2023). "The results showed that SNHG4 expression was elevated in tumor tissues (n = 60) compared with adjacent normal tissues (n = 60) and normal prostate tissues from BPH patients (n = 30)." (PMID 37596700, 2023). "According to the qRT‒PCR results, SNHG4 was highly expressed in tumor tissues with a high Gleason score." (PMID 37596700, 2023). "Meanwhile, we observed that higher SNHG4 expression was remarkably related with larger tumor size, microvascular invasion, and higher TNM and Edmonson stages." (PMID 36565037, 2023). "Then, SNHG4 promotes ZIC5 expression via miRNA-377 sponging to enhance survival of tumor cells and increase malignant behavior." (PMID 35773731, 2022). "Investigators found that overexpressed SNHG4 was closely related to advanced tumor grade, stage, and OS." (PMID 36081998, 2022). "In some non-neoplastic diseases, in addition to affecting proliferation, SNHG4 is closely related to the immune response and can play dual pro-inflammatory and anti-inflammatory roles." (PMID 34717631, 2021). "As shown in, SNHG4 silencing reduced, whereas miR-590-3p inhibition increased, the tumor volume and tumor weight; the effects of SNHG4 silencing on tumor growth were significantly reversed by miR-590-3p inhibition." (PMID 33744866, 2021). "SNHG4 plays a carcinogenic role in most tumour diseases, and it can promote cancer cell proliferation and migration and inhibit apoptosis." (PMID 34717631, 2021). "Reducing the expression of SNHG4 can inhibit the proliferation of tumour cells and is expected to become a potential target for cancer treatment." (PMID 34717631, 2021).
tumor (continued). "The results showed that high SNHG4 expression was closely related to relapse status, poor tumour grade, advanced T stage, lymph node invasion, and distant metastasis." (PMID 34717631, 2021). "As a further confirmation of the in vitro findings, SNHG4 silencing in subcutaneously transplanted tumors inhibited tumor growth by decreasing cell cycle regulators, whereas miR-590-3p inhibition exerted the opposite effects." (PMID 33744866, 2021). "In vivo, SNHG4 silencing inhibited subcutaneously transplanted tumor growth and decreased cell cycle marker levels, whereas miR-590-3p inhibition exerted the opposite effects." (PMID 33744866, 2021). "Univariate and multivariate Cox regression analysis indicated that SNHG4 expression was an independent prognostic factor for poor survival and tumor recurrence in patients with RCC." (PMID 33088220, 2020). "Small nucleolar RNA host gene 4 (SNHG4) is reported to play an essential role in tumor growth and progression." (PMID 33088220, 2020). "In this work, we initially confirmed the up-regulated SNHG4 level in GC tumor samples and cells." (PMID 39735673, 2025). "Overall, the data suggested that SNHG4 accelerated the HCC tumor growth in vivo." (PMID 36565037, 2023). "In addition, we observed significantly high SNHG4 expression in tumor samples with high Gleason scores." (PMID 37596700, 2023). "SNHG4 is known to play an oncogenic role in tumors, and decreased expression of SNHG4 may inhibit tumor cell proliferation; therefore, it is a potential target for cancer treatment." (PMID 37189636, 2023). "The results suggested that SNHG4 is highly expressed in the PCa tumor group." (PMID 37596700, 2023). "Our findings indicated that SNHG4 could be a key tumor promoter and a potential therapeutic target for HCC." (PMID 36565037, 2023). "Patients with high SNHG4 expression had a higher tumour recurrence and a lower survival rate." (PMID 34717631, 2021). "In addition, we found that SNHG4 could be a potential therapeutic strategy given its mechanistic role in promoting tumor invasion, cell proliferation, and colony formation by regulating EMT and SP-1 signaling pathways." (PMID 37189636, 2023). "In addition, lncRNA SNHG4 is highly expressed in OS tissues and cell lines, miR-377-3p is downregulated in OS, and SNHG4 acts as a competing endogenous RNA with sponge miR-377-3p to promote OS tumor proliferation and migration." (PMID 36059961, 2022). "The expression levels of SNHG4 in TCGA database were analyzed using UALCAN website, including multiple tumor tissues and normal tissues." (PMID 39951205, 2025). "By avoiding the arrest of the cell cycle and enhancing proliferation and spread of tumor cells, In gastric cancer, RRM2 is upregulated through miRNA-204-5p when SNHG4 is overexpressed." (PMID 39512820, 2024). "An examination of tumor specimens revealed an escalation in the expression of KIF18A, in conjunction with heightened levels of CENPE, SNHG4, KIAA1841, CDCA2, and PRR11 mRNA." (PMID 38495502, 2024). "Then, SNHG4 stimulates the production of ZIC5 by the sponging of miRNA-377, which has the effect of increasing the malignant behavior of tumor cells and enhancing their survival (Wang ZY." (PMID 39512820, 2024). "We found that SNHG4 enhanced the proliferative, migratory and invasive capacities of HCC cell line, and facilitated the tumor growth in vivo." (PMID 36565037, 2023). "The SNHG4/miR-590-3p/CDK1 axis influences the cell cycle to modulate CRC cell proliferation and subcutaneously transplanted tumor growth." (PMID 33744866, 2021). "Increased SNHG4 expression stimulated proliferation, migration, and invasion inhibited apoptosis of RCC cells in vitro and promoted tumor growth in vivo." (PMID 34884928, 2021). "SNHG4 sponges miR-10a to upregulate PTEN, which acts as a tumour suppressor and can inhibit cancer cell proliferation." (PMID 34717631, 2021).
tumor (continued). "Furthermore, high expression of SNHG4 was significantly associated with advanced T stage, node invasion, distant metastasis status, high University of California, Los Angeles, Integrated Staging System (UISS) score category, poor tumor grade, and relapse status." (PMID 33088220, 2020). "In univariate analysis, advanced tumor stage/pathological stage/histological grade, metastasis, increased SNHG3/SNHG4 expression and decreased SNHG5/SNHG8 expression were potential risk factors of shorter OS." (PMID 32126023, 2020). "Further mechanical studies demonstrated that SNHG4 functioned as a ceRNA to sponge miR-204-5p, then upregulate RUNX2, to promote RCC tumor progression." (PMID 33088220, 2020). "The present data showed that RUNX2, a well-known transcription factor that participated in tumor EMT, migration, and invasion, was recognized as the downstream target of miR-204-5p and had a competition with SNHG4 to interact with miR-204-5p in RCC cell lines." (PMID 33088220, 2020). "Based on the RNA sequencing analysis, which identified lncRNA SNHG4 as a potential regulator of TNBC progression, we sought to determine whether overexpression of SNHG4 could promote tumor progression." (PMID 40657248, 2025). "However, the study of lncRNA SNHG4 in TNBC remains limited, particularly regarding its role in TNBC patient serum exosomes and its impact on tumor progression." (PMID 40657248, 2025). "The positive correlation between SNHG4 and CREB5 were detected in HCC tumor tissues we collected." (PMID 36565037, 2023). "Moreover, the expression of SNHG4, TK1, AURKA, RRM2 and EZH2 in the tumor tissues was found to be significantly elevated after SNHG4 overexpression." (PMID 37596700, 2023). "SNHG4 overexpression in gastric cancer leads to RRM2 upregulation via miRNA-204-5p down-regulation to prevent cell cycle arrest and to enhance growth and metastasis of tumor cells." (PMID 35773731, 2022). "In this paper, we mainly summarized the research progress regarding SNHG4 in most tumours and some non-tumour diseases." (PMID 34717631, 2021). "Regarding cell cycle markers, SNHG4 silencing increased, whereas miR-590-3p inhibition decreased, the protein levels of CDK1, cyclinB1, and cyclinA2 in the tumor samples; the effects of SNHG4 silencing on cell cycle markers were also significantly reversed by miR-590-3p inhibition." (PMID 33744866, 2021). "Furthermore, the dataset from TCGA-KIRC showed that miR-204-5p expression possessed a negative correlation with SNHG4 and was significantly decreased in tumor tissues compared with normal renal tissues." (PMID 33088220, 2020).
cancer (20 papers, 2018 to 2025). A tumor composed of atypical neoplastic, often pleomorphic cells that invade other tissues. "Recent studies have shown that SNHG4 is highly expressed in various cancers and is involved in regulating multiple cancer-related biological processes, making it closely associated with clinical pathological features and prognosis in some cancers." (PMID 40657248, 2025). "Numerous studies have shown that SNHG4 is upregulated in various cancers, where its activity is implicated in cell proliferation, invasiveness, migration, and inhibition of apoptosis." (PMID 36140769, 2022). "Interestingly, as a recently discovered lncRNA located in 5q31.2, the small nucleolar RNA host gene 4 (SNHG4), has been implicated in various human cancers." (PMID 33816782, 2021). "To date, there have been several studies on SNHG4 and cancer, but they are mainly in the basic research stage, and more clinical application studies are needed in the future." (PMID 37189636, 2023). "High SNHG4 expression is closely related to the clinical–pathological features and prognosis of some cancers; high expression of SNHG4 represents a worse prognosis." (PMID 36672893, 2023). "In inhibiting the survival and development of cancer cells, targeted inhibition of SNHG4 appears to be beneficial." (PMID 36672893, 2023). "The Cancer Genome Atlas (TCGA) data show that SNHG4 is upregulated in many cancers, including RCC, and Wu and colleagues confirmed its high expression in RCC." (PMID 34717631, 2021). "It has been reported that SNHG4 promotes migration, invasion, and metastasis in a variety of cancers." (PMID 34717631, 2021). "SNHG4 has been identified in several physiological and pathological processes, participating in cancers." (PMID 32454787, 2020). "In fact, ccRCC was the cancer type where both SNHG4 and PRR7-AS1 were most frequently altered." (PMID 33333852, 2020). "These indicate that SNHG4 exert a crucial role in various cancers." (PMID 32454787, 2020). "Among them, SNHG4 and NEAT1 drew our attention for their complex biological functions in cancer regulation." (PMID 37596700, 2023). "The expression of SNHG4 in TT was significantly higher than that in ANT, which was also confirmed in the dataset from the cancer genomic atlas (TCGA)-kidney renal clear cell carcinoma (KIRC)." (PMID 33088220, 2020). "While the mechanism of SNHG4 and LINC00523 on cancer initiation and progression is remained elusive." (PMID 30430424, 2019).
respiratory diseases (1 paper, 2023). "In recent years, there are more and more reports on non-coding RNA in respiratory diseases, but the role and mechanism of SNHG4 in regulating the miR-144-3p/EZH2 axis in COPD and bronchial epithelial cells have not been reported at home and abroad." (PMID 38114929, 2023).
SNHG4 also shares sentences with these, for which no sentence is quoted: non-small cell lung carcinoma (3 papers); bladder cancer (1); breast carcinoma (1); diffuse large B-cell lymphoma (1); infection (1); ovarian carcinoma (1); Pain (1); rheumatoid arthritis (1).